ABCG2 (ATP binding cassette subfamily G member 2 (JR blood group))
Description:
Broad substrate specificity ATP-dependent transporter of the ATP-binding cassette (ABC) family that actively extrudes a wide variety of physiological compounds, dietary toxins and xenobiotics from cells. Involved in porphyrin homeostasis, mediating the export of protoporphyrin IX (PPIX) from both mitochondria to cytosol and cytosol to extracellular space, it also functions in the cellular export of heme. Also mediates the efflux of sphingosine-1-P from cells. Acts as a urate exporter functioning in both renal and extrarenal urate excretion. In kidney, it also functions as a physiological exporter of the uremic toxin indoxyl sulfate (By similarity). Also involved in the excretion of steroids like estrone 3-sulfate/E1S, 3beta-sulfooxy-androst-5-en-17-one/DHEAS, and other sulfate conjugates. Mediates the secretion of the vitamins riboflavin and biotin into milk (By similarity). Involved in the excretion of the riboflavin-derived compound lumichrome into the intestinal lumen and in its secretion into milk. Extrudes pheophorbide a, a phototoxic porphyrin catabolite of chlorophyll, reducing its bioavailability (By similarity). Plays an important role in the exclusion of xenobiotics from the brain (Probable). It confers to cells a resistance to multiple drugs and other xenobiotics including mitoxantrone, pheophorbide, camptothecin, methotrexate, azidothymidine, and the anthracyclines daunorubicin and doxorubicin, through the control of their efflux. In placenta, it limits the penetration of drugs from the maternal plasma into the fetus (By similarity). May play a role in early stem cell self-renewal by blocking differentiation (By similarity). In inflammatory macrophages, exports itaconate from the cytosol to the extracellular compartment and limits the activation of TFEB-dependent lysosome biogenesis involved in antibacterial innate immune response.
Synonyms: CD338; ABCP; BCRP; MXR; EST157481; ABC15; BMDP; CDw338; CDw388; GOUT1; MRX; MXR-1; MXR1; UAQTL1
Tractability: Small molecule: a structure with a bound ligand is known; a high-quality ligand is known; it belongs to a druggable protein family. Antibody: UniProt places it where antibodies can reach, with high confidence; its Gene Ontology location is reachable by antibodies, with high confidence; UniProt predicts a signal peptide or a membrane-spanning region. PROTAC: ubiquitination databases record sites on it; its protein half-life has been measured; a small molecule that binds it is known.
Target class: ATP-binding cassette; Transporter; Primary active transporter; ABCG subfamily
Chemical probes: CHEMBL3092485, KS176, Ko 143, ML230
Safety:
Unwanted effects reported when the protein is acted on. In parentheses: how it was acted on, where the effect was seen, and who reports it.
abnormal dreams (source: ClinPGx)
adverse events (source: ClinPGx)
anemia (source: ClinPGx)
diarrhea (source: ClinPGx)
drug toxicity (source: ClinPGx)
grade 3-4 nonhematological toxicity (source: ClinPGx)
longer progression-free survival (source: ClinPGx)
mucositis (source: ClinPGx)
shorter progression-free survival (source: ClinPGx)
statin-related myopathy (source: ClinPGx)
thrombocytopenia (source: ClinPGx)
tumor response rate (source: ClinPGx)
tumor response rate and grade 3-4 nonhematological toxicity (source: ClinPGx)
Gene: Protein-coding gene on chromosome 4 (88,090,150 to 88,231,818, reverse strand). Ensembl gene ENSG00000118777.
Subcellular location: Cell membrane; Apical cell membrane; Mitochondrion membrane
Subcellular location (Human Protein Atlas): Plasma membrane; Nucleoplasm
Pathways (Reactome):
Drug ADME: Abacavir transmembrane transport; Ciprofloxacin ADME; Paracetamol ADME
Metabolism: Heme biosynthesis; Heme degradation; Sphingolipid de novo biosynthesis
Cellular responses to stimuli: NFE2L2 regulating MDR associated enzymes
Developmental Biology: Differentiation of Keratinocytes in Interfollicular Epidermis in Mammalian Skin
Transport of small molecules: Iron uptake and transport
Gene Ontology:
Molecular function: ABC-type xenobiotic transporter activity; ATPase-coupled transmembrane transporter activity; efflux transmembrane transporter activity; identical protein binding; protein binding; protein homodimerization activity; riboflavin transmembrane transporter activity; urate transmembrane transporter activity; biotin transmembrane transporter activity; transmembrane transporter activity; xenobiotic transmembrane transporter activity; ABC-type transporter activity; ATP binding; ATP hydrolysis activity; protein dimerization activity
Biological process: cellular detoxification; renal urate salt excretion; riboflavin transport; transepithelial transport; transmembrane transport; urate metabolic process; xenobiotic detoxification by transmembrane export across the plasma membrane; xenobiotic transport across blood-brain barrier; biotin transport; export across plasma membrane; sphingolipid biosynthetic process; sulfite export across plasma membrane; transport across blood-brain barrier; detoxification; lipid transport; urate transport; xenobiotic transport
Cellular component: apical plasma membrane; brush border membrane; membrane raft; mitochondrial membrane; plasma membrane; external side of apical plasma membrane; membrane
Genetic constraint (gnomAD): Loss-of-function variants: 78 observed, 71.97 expected, observed/expected ratio (o/e) 1.08, 90% interval 0.9 to 1.31. The upper end of that interval is the gene's LOEUF score, 1.31, which puts it in group 5 of 6, group 1 being the genes least tolerant of losing a copy. Missense variants: 733 observed, 771.7 expected, observed/expected ratio (o/e) 0.95, 90% interval 0.89 to 1.01. Synonymous variants: 249 observed, 279.18 expected, observed/expected ratio (o/e) 0.89, 90% interval 0.8 to 0.99.
Homologues: Orthologues: chimpanzee ABCG2 (99% identical), pig ABCG2A (85% identical), dog ABCG2 (83% identical), tropical clawed frog abcg2 (69% identical), mouse Abcg3 (55% identical), rat Abcg3l1 (53% identical), rat Abcg3 (52% identical), rat Abcg3l4 (51% identical), rat Abcg3l4 (50% identical), zebrafish abcg2b (45% identical), Caenorhabditis elegans wht-1 (28% identical), Caenorhabditis elegans wht-4 (25% identical), and 4 more. Paralogues in human: ABCG1 (27% identical), ABCG8 (27% identical), ABCG4 (27% identical), ABCG5 (24% identical).
Diseases named in the same sentence as ABCG2 in open-access papers:
ABCG2 is named in the same sentence as 409 diseases in open-access papers, as found by Europe PMC text mining. Sharing a sentence is not in itself a finding about the gene and the disease. The quoted sentences say what the papers report.
breast cancer (528 papers, 2002 to 2026). A primary or metastatic malignant neoplasm involving the breast. "ABCG2, for its part, is the main transporter associated with drug efflux in resistance associated with mammary cancer, where it can transport chemotherapeutic drugs such as mitoxantrone and other anthracyclines." (PMID 38672378, 2024). "Simultaneously, a novel half transporter member of the ABC superfamily was identified from a resistant breast cancer cell line, hence named as breast cancer resistance protein (BCRP, encoded by the ABCG2 gene)." (PMID 36677553, 2023). "It was shown that in the later stages of breast cancer, which is associated with drug resistance, ABCG2 gene expression increases, which leads to a more frequent appearance of this protein on the cell membrane." (PMID 37166017, 2023). "A number of studies have demonstrated that ABCG2 is associated with tumor chemoresistance in breast cancer." (PMID 37569629, 2023). "An additional subpopulation of CD44+/CD24+ cells of the BRCA1-mutated basal-A/basal-like breast cancer was sorted using an antibody against CD338 (ABCG2 antigen) and found to be enriched in several stemness markers." (PMID 36834918, 2023). "This suggested that the expression of ABCG2/CD338 proteins was specific to the tumor-initiating luminal progenitor subpopulation of BRCA1-mutated breast cancer cells." (PMID 36834918, 2023). "In contrast to ABCB1, ABCG2 protein and mRNA expression has been demonstrated in breast cancer, and can be linked to therapy response." (PMID 37147730, 2023). "ABCG2 34GA and ABCG2 34AA genotypes were substantially linked to an increased risk of breast cancer." (PMID 37324630, 2023). "Our previous study showed that changes in the expression levels of several ABC genes (ABCB1, ABCC1, ABCC2, ABCC5, ABCG1, and ABCG2) during neoadjuvant chemotherapy (NAC) were associated with the response to this therapy in breast cancer patients." (PMID 35631534, 2022). "In conclusion, mdr1 and ABCG2 genes are frequently mutated in breast cancer patients compared with controls and mRNA expression has been altered due to these mutations." (PMID 37092084, 2022). "This is a two parts study; a meta-analysis exploring association of drug resistance (mdr1 and ABCG2) genes with breast cancer and mutational association with molecular subtypes of cancer." (PMID 37092084, 2022). "Present study was designed to observe the mutational spectrum and mRNA expressional variations of mdr1 and ABCG2 and its association with different environmental, clinical, and histopathological parameter in breast cancer patients in Pakistani population." (PMID 37092084, 2022). "Unfortunately only one report was found detailing the mutational analysis of ABCG2 gene with breast cancer however its association with other cancers has been reported in many studies." (PMID 37092084, 2022). "Examples are variants in ABCB1 that can predict toxicity and response to chemotherapy in breast cancer and ABCG2 and ABCC10 variability that associates with tyrosine kinase inhibitor and taxane toxicity in non-small cell lung cancer." (PMID 35715537, 2022). "Association of ABCG2 gene mutations with untreated breast cancer was reported only by one study so far." (PMID 37092084, 2022). "BCRP, encoded by the ABCG2 gene, was initially identified from a multidrug resistant breast cancer cell line that confers resistance to chemotherapeutic drugs." (PMID 33494365, 2021). "We previously demonstrated the abnormal activation of β-catenin and the subsequent upregulation of its downstream gene ABCG2 were tightly associated with drug-resistant properties of breast cancer." (PMID 34149413, 2021). "First cloned from doxorubicin-resistant breast cancer cells, the human ABCG2 gene encodes ATP binding cassette (ABC) transporters that drive the transport of various substrates across cell membranes." (PMID 33509236, 2021).
breast cancer (continued). "Breast cancer resistance protein (BCRP), encoded in the human body by the ABCG2 gene, was first identified in a drug-resistant human breast cancer cell line." (PMID 34680470, 2021). "Nevertheless, mammary tumour latency was shortened in Abcg2-deficient female K14cre; Brca1F/F; p53F/F mice compared with their Abcg-2 proficient counterparts." (PMID 33801148, 2021). "The overexpression of the transporters, such as ABCB1, known as P-glycoprotein, P-gp, ABCG2, known as breast cancer resistant protein, BCRP, and ABCC1, known as multidrug resistance-associated protein 1, MRP1, contributes to MDR." (PMID 32365495, 2020). "The overexpression of ABCG2 transporter, which is one of the ABC transporters, also called BCRP, is known to cause drug resistance in breast cancers." (PMID 33333736, 2020). "ABCG2, or breast cancer resistance protein, is the major drug efflux transporter in breast cancer associated resistance, as indicated by the name." (PMID 34322663, 2019). "In the present study, single nucleotide polymorphisms (SNPs) from the ABCC1, ABCC2, ABCB1, and ABCG2 genes were screened in breast cancer patients and healthy volunteers from the Jordanian-Arab population." (PMID 31391850, 2019). "Of these, ABCG2 (also known as breast cancer resistance protein) is an ATP-binding cassette transporter associated with the cancer stem cell phenotype and chemotherapeutic resistance, including therapy-refractory breast cancer." (PMID 29361610, 2018). "ABCB1 3435TT and ABCG2 421CC were significantly associated with longer PFS in Chinese breast cancer patients." (PMID 29340035, 2017). "Following the identification of the expression of this protein as the cause of acquired multidrug resistance (MDR) in breast cancer cell lines, ABCG2 has been termed breast cancer resistance protein." (PMID 28082903, 2016). "For example, in breast cancer, C6 ceramide-induced secretion of breast cancer resistance protein (BCRP/ABCG2-associated exosomes) and inhibition of nSMase2 restored the cellular BCRP." (PMID 26587537, 2015). "We found that ABCG2 G34A GA/AA genotype, C421A AA genotype, and haplotypes 34A-421C and 34G-421A were significantly associated with increased risk for developing breast carcinoma." (PMID 26634205, 2015). "Well-known ABC transporters include the multidrug resistance (MDR) protein or P-glycoprotein (MDR1, P-gp, ABCB1); the multidrug resistance-associated proteins (MRP1, ABCC1); and the breast cancer resistance proteins (BCRP, ABCG2)." (PMID 23837843, 2013). "In our model, we found that EZN-2208 results in durable responses of ABCG2-expressing BRCA1-deficient mammary tumors, in contrast to topotecan or irinotecan treatment." (PMID 23028879, 2012). "Although a significant body of literature has linked ABCG2 expression with drug resistance in breast cancer, considerably less is known about ABCA5 and ABCC5 in this disease." (PMID 23174366, 2012). "Using a genetically engineered mouse model for BRCA1-deficient breast cancer, we investigated therapeutic strategies to overcome ABCG2-mediated resistance to clinically used topoisomerase I inhibitors." (PMID 23028879, 2012). "Previously, we treated ABCG2-deficient mammary tumors with topotecan-olaparib combination therapy and observed improved tumor response compared with topotecan monotherapy." (PMID 23028879, 2012).
breast cancer (continued). "Studies report that MPs can upregulate efflux transporters (ABCB1/ABCG2) and alter chemotherapeutic susceptibility, enhance metastatic features in breast cancer, promote therapy resistance via ASGR2 in gastric cancer, and aggravate radiation-induced intestinal injury." (PMID 41378310, 2025). "Also, overexpression of miR-548k in breast cancer cells is associated with decreased ABCG2 gene expression, another key player in AD." (PMID 38338859, 2024). "The P-gp transporter and MDR-associated proteins, MRP1 and ATP binding cassette subfamily C member 1 (ABCC1), are particularly relevant to cancer chemotherapy, as are the breast cancer resistance proteins, BCRP and ABCG2, which are encoded by GTPase-activating protein MDR1 (MDR1) genes." (PMID 37450923, 2024). "Similarly, the combination of GS and bexarotene increased DOX retention in breast cancer cells and enhanced cell death through increased secretion of exosome-associated BCRP/ABCG2 and reduced MDR levels." (PMID 36046484, 2020). "ABCG2 gene is associated with multidrug resistance, especially in breast cancer." (PMID 30672151, 2019). "For instance, ABCC1 and ABCG2 have been associated with chemoresistance in breast cancer." (PMID 28912626, 2017). "However, a high mutation rate of both ABCB1 C3435T and ABCG2 C421A (16% and 17%, respectively) was observed in breast cancer tissues." (PMID 29340035, 2017). "Further analysis showed that ASCL1 knockdown resulted in the downregulation of the ATP-binding cassette transporter (ABCG2), a protein linked to drug resistance in BC, also known as the breast cancer resistance protein." (PMID 39963143, 2025). "While HIF-2α expression has also been associated with high ABCG2 expression, histology-grade and Ki67 expression in invasive human breast cancer, suggesting that HIF-2α could be a reliable prognostic marker for development of drug resistance and metastasis in breast cancer." (PMID 36831452, 2023). "Overexpression of the ABC drug transporter ABCG2 has been linked to acquired resistance to a wide range of clinically relevant anticancer agents and across multiple malignances, including non-small cell lung, thyroid, and breast cancer cells as well as hematological malignancies." (PMID 32059437, 2020). "For instance, we previously found that CPT inhibits ABCG2 oligomerization, yet it has also been shown to activate MAPK signaling in ERα-deficient breast cancer cells." (PMID 41541684, 2026). "Pro‐inflammatory cytokines such as IL‐1β and TNF‐α further amplify this effect by stimulating both NF‐κB signaling, and ABCG2 expression in certain breast cancer cell lines, suggesting a coordinated response involved in drug resistance." (PMID 40654246, 2025). "Deep deletions were significantly more prevalent in prostate cancer than in breast cancer, with frequent occurrences in ABCG2, ABCG1, ABCC4, ABCA2, ABCC2, ABCC7/CFTR, and ABCC9." (PMID 40641097, 2025). "The representative tetrahydro-β-carboline analogs that have been discovered for their anti-tumor mechanism are as follows: inhibitors of mitotic kinesin Eg5 and inhibitors of breast cancer resistant ATP-binding cassette sub-family G member 2(ABCG2)." (PMID 40508205, 2025). "The overall frequency of genetic alterations in breast cancer ranged from 1% in ABCG2 to 9% in ABCC3." (PMID 40641097, 2025). "ABCG2 is upregulated in the extracellular vesicle (EV) membranes of neighboring breast cancer cells, and actively pumps chemotherapeutic drugs from the cytosol into the vesicle lumen, resulting in an MDR phenotype." (PMID 40612109, 2025).